IL6 (interleukin 6)
Diseases named in the same sentence as IL6 in open-access papers (continued):
Sharing a sentence is not in itself a finding about the gene and the disease.
colitis (continued). "The activation of IL-6/STAT3 pathway is involved in the occurrence and development of colitis." (PMID 35982893, 2022). "Cyanidin-3-glucoside and cyanidin were reported to downregulate the proinflammatory mediator nitric oxide, as well as proinflammatory cytokines TNF-α, IL-1β, IL-6, and IFN-γ in 2,4,6-trinitrobenzenesulfonic acid (TNBS)-induced colitis mice and lipopolysaccharide (LPS)-stimulated Caco-2 cells." (PMID 35204188, 2022). "We also confirmed that during colitis, a lack of mPGES-1 facilities increased expression levels of IL-1β, in addition to IL-6." (PMID 34983695, 2022). "Next, we compared levels of TNF-α and IL-6 in colitis mice in the presence and absence of MBZ using ELISA assay." (PMID 35715495, 2022). "Inflammatory cytokines (IL-6 and TNF-α) levels were significantly (p < 0.05) increased in the colon tissue of DSS-induced colitis mice when compared with the control group, while LCS-SeNPs significantly reduced (p < 0.05) the levels of pro-inflammatory cytokines IL-6 and TNF." (PMID 36555167, 2022). "This is accompanied by significantly higher serum levels of IL-6 and TNF-α in mice with colitis." (PMID 34983592, 2022). "In DSS-induced colitis, mice that were fed experimental diets containing AST (100–200 ppm) exhibited lowered gene expressions of several inflammatory markers including TNF-α, IL-1β, IL-6, COX-2, and iNOS and inhibited NF-κB expression in the colon." (PMID 36555112, 2022). "In this study, we observed that HZJDD remarkably reduced the level of IL-6, CRP, and TNF-α in DSS-induced colitis rats, indicating that HZJDD could exert anti-inflammatory effects against DSS-induced in UC rats." (PMID 36313293, 2022). "All the rats exposed to 3% DSS for 7 days developed acute colitis, as evidenced by the increase in the DAI, the shortening in the colon length, and the increase in the mRNA relative abundance of the pro-inflammatory cytokines IL-1β, IL-6, and TNF-α." (PMID 35628158, 2022). "TLR4 is a Toll-like receptor and has been reported to have a repairing effect on DSS-induced intestinal injury and up-regulation of IL6, CCL2 and CSF3, which may also be related to their therapeutic effects on TNBs-induced colitis." (PMID 35831878, 2022). "Not surprisingly, C3G inhibited NF-κB phosphorylation, reduced mRNA expression of pro-inflammatory cytokines including IL-1β, IL-6, IL-8, COX-2, and TNF-α, and protein levels of apoptosis related genes in DSS-induced colitis mice, providing new ideas for using C3G as adjuvant agent for treating UC." (PMID 35805952, 2022). "Experimentally, treatment with yeast worsened the DAI in DSS colitis and exacerbated ASCA levels, in addition promoted serum and colonic tissue pro-inflammatory cytokine secretion (TNF- α, IL-1β and IL-6) and stimulated the expression of NF-κB in colonic tissue." (PMID 36384756, 2022). "Colitis in the dual treated mice (i.e., LF82 + DSS) was accompanied by elevated proinflammatory cytokines in the colonic tissues including IL-17, IFNγ, IL-1β, and IL-6 compared to the mice treated with DSS only." (PMID 35381031, 2022). "Unexpectedly, the stress sensitization of colitis was not stopped in IL-6 knockout mouse models, which suggestes that a high inflammatory response was not the main cause of the chronic stress-aggravated colitis." (PMID 36275694, 2022). "The DSS-induced colitis mouse model is primarily a macrophage/Th1/Th17 driven inflammatory model with increased levels of pro-inflammatory cytokines such as TNF-α, IL-1β and IL-6." (PMID 36365201, 2022). "In addition, the plasma levels of granulocyte colony-stimulating factor (G-CSF), IL-6, IL-17, TNF-α, and chemokine ligand 1 (CXCL1) were significantly increased in the colitis model." (PMID 36009796, 2022). "Thus, a significant increase in mRNA of TNF, IL-6, IL-1β, and ICAM-1 genes in the proximal colon in mice with DSS-induced colitis compared with control mice." (PMID 36359839, 2022).
colitis (continued). "Our results showed that LCS-SeNPs reduced the pro-inflammatory cytokines TNF-α and IL-6 levels in serum and the colon of DSS-induced colitis mice, suggesting that LCS-SeNPs can achieve anti-inflammatory effects by reducing the serum levels of pro-inflammatory factors TNF-α and IL-6." (PMID 36555167, 2022). "Hesperidin also reduced colitis by attenuating MDA, MPO, and IL-6." (PMID 35566252, 2022). "The sequel of events triggered by TLR-4 activation, including NF-kB and NLRP3 activation, and the release of IL-1β, IL-6, and TNF-α, are considered the most involved in persistent intestinal inflammation triggering and maintenance during colitis, and HIV-1 Tat-induced diarrhea." (PMID 36009057, 2022). "Moreover, the effect of LCS-SeNPs on intestinal oxidative stress and permeability were evaluated by measuring the levels of TNF-α, IL-6, GSH-Px, LPS and DAO in the serum of mice with DSS-induced colitis." (PMID 36555167, 2022). "Furthermore, VNS significantly improved the multivariate index of colitis in rats with TNBS-induced colitis and chronic VNS in the same model improved colitis and decreased the production of pro-inflammatory cytokines (TNF-α and IL-6)." (PMID 34983592, 2022). "In a colitis experimental model of colitis, vitexin significantly inhibited the TNF-α, IL-6, and IL-1β expression, suggesting that this compound may suppress the inflammatory response to improve colitis-induced liver damage." (PMID 35164352, 2022). "AL-1 ameliorated DSS-induced colitis in mice by inhibiting NF-κB and MAPK signaling pathways, reduced iNOS, COX-2, NO and PGE2 in cultured macrophages, significantly reduced production of IL-1β, IL-6, TNF-α, PGE2 and IFN-γ, and increased secretion of IL-10." (PMID 36238575, 2022). "A previous study showed that peanut shell extract (PSE) significantly alleviated inflammatory bowel disease (IBD) symptoms and reduced the inflammation in a rodent model of colitis as it markedly reduced the levels of pro-inflammatory cytokines as TNF-α and IL-6." (PMID 35326112, 2022). "In conclusion, our results revealed that oral administration of BCP in DSS-induced ulcerative colitis mice improved colitis by reducing MPO activity, IL-1β, IL-6, and TNF-α concentrations, as well as the abundance of bacteria that cause intestinal immune imbalance." (PMID 36431883, 2022). "Furthermore, CHR down-regulates LPS-elicited TNF-α, IL-6, and COX-2 expressions by suppressing the activation of NF-κB and Caspase-1, helping resist colitis." (PMID 35599576, 2022). "(100, 300 mg/kg) could improve the syndrome of TNBS-induced colitis mice by regulating the MPO and MDA contents and the levels of pro-inflammatory (TNF-α, IL-6, L-1β, IL-12, IFN-γ, IL-2, IL-17) cytokines and anti-inflammatory cytokines (IL-4, IL-10)." (PMID 36160392, 2022). "While reduced TNF expression is consistent with the immunomodulatory effects of HF reported in colitis, it is unclear why levels of IL-6 and IL-10 are not similarly affected." (PMID 35296081, 2022). "(540 mg/kg) could not only promote BMSC homing to the injured tissue and regulate cytokines such as IL-6, IL-10, IL-17 A, and TGF-β for preventing TNBS-induced rats colitis but also promote the migration of IEC in vitro and influence multiple genes." (PMID 36160392, 2022). "Moreover, B. vulgatus Bv46 treatment reduced the expression of colonic TNF-α, IL-6 and IL-1β in the DSS-induced mouse colitis in vivo and the TNF-α, IL-6 and IL-1β release in the supernatants of LPS-activated macrophage cells in vitro." (PMID 36531989, 2022). "The results showed that ERE treatment alleviated DSS-induced colitis, which was characterized by decreases in disease activity index (DAI) scores, spleen index and colon levels of TNF-α and IL-6, mitigation in pathological damage and oxidative stress and increases in colon length and IL-10 levels." (PMID 36295859, 2022).
colitis (continued). "Furthermore, there was a difference (p < 0.05) with increased levels of IL-6 in the hippocampus of colitis mice treated with HEBD and the naive group compared with the vehicle-treated colitis group." (PMID 35295931, 2022). "On the other hand, the colonic expression levels of IL-1β and IL-6, which were known to be major macrophage cytokines, were significantly higher in mPGES-1−/− mice than in WT mice under either the GK1.5 or LTF2 treatment during DSS-induced colitis." (PMID 34983695, 2022). "IL-6 stimulation enhances YKL-40 production; therefore, blocking IL-6-mediated production of YKL-40 could help prevent inflammation and subsequent colitis-mediated carcinogenesis in epithelial cells." (PMID 34203467, 2021). "In the present study, it was found that serum levels of tumor necrosis factor-α (75 vs. 44 pg./ml), interleukin-6 (41 vs. 21 pg/ml), and nitric oxide (24 vs. 6 μm/ml) in TNBS-induced untreated colitis treatment were significantly increased as compared to healthy control." (PMID 34912469, 2021). "In addition, we found that after GL administration, the plasma levels of IL-6 and TNF-α in the CC + GL group were lower than those in the CC group, suggesting that GL attenuates inflammation in AOM/DSS-induced colitis." (PMID 33807620, 2021). "In addition, we found that curcumin promoted the release of the anti-inflammatory cytokines IL-10 and IL-33 in colitis mice and inhibited the secretion of the proinflammatory cytokines CCL-2, IL-1β, and IL-6." (PMID 34567209, 2021). "As TNFα, IL-1β, and IL-6 play crucial roles in the pathogenesis of colitis and cinacalcet suppressed the production of those inflammatory cytokines, we assessed the anti-inflammatory effect of cinacalcet on DSS-induced colitis." (PMID 34880751, 2021). "Our data indicate that IL-6-mediated IL-6ST/gp130 signalling drives STAT3 activation, by which STAT3 modulates intestinal permeability through the expression of tight junction proteins during the development of colitis." (PMID 33673239, 2021). "As well, decreased levels of IL-1β, IL-6, IL-8, and TNF-α in the plasma, and decreased levels of IL-6 and TNF-α, and increased level of MPO in the colon were shown in mice with colitis treated by EGCG-FMT compared with other three groups." (PMID 34493333, 2021). "The majority of published studies performed using the experimental models of colitis have indicated that the altered immune response was correlated with the increasing release of pro-inflammatory cytokines, including IFN γ, TNFα, IL-6, IL-1β, GM-CSF, and IL-17A." (PMID 34970585, 2021). "The mice develop (histological) inflammation at the axial and peripheral entheses 1 week after curdlan induction followed by development of clinical enthesitis, sacroiliitis, peripheral arthritis and colitis and uveitis with increased serum levels of IFN-γ, TNF-α, IL-6 and IL-17A." (PMID 34267743, 2021). "When colitis in mice was induced via IL-10−/−, it was shown that the disease worsened in combination with SERT deletion, which was accompanied by increased levels of IL-6 and TNF-α mRNAs." (PMID 34502396, 2021). "IAP requires TLR4 signaling to mediate its anti-inflammatory effects, as IAP ameliorated colitis and inhibited IL-6 and TNF-α production in WT but not in TLR4-KO mice." (PMID 34944428, 2021). "Furthermore, orally gavaged or intraperitoneally injected buspirone alleviated colitis: it reduced myeloperoxidase activity, TNF-α and IL-6 expression, and NF-κB+/CD11c+ cell population." (PMID 33731795, 2021). "Current findings indicated that the administration of 400 mg/kg Aloe vera extract rectally on experimental colitis in rats can significantly attenuate the increased levels of TNF-a, IL-6, NO, MPO, and MPA and reduce the inflammations as compared to the TNBS-induced colitis model." (PMID 34912469, 2021). "Moreover, prophylactic EGCG tended to reduce the plasma levels of IL-1β, IL-6, IL-8, and TNF-α in mice with colitis." (PMID 34493333, 2021).
colitis (continued). "Moreover, sodium butyrate was reported to ameliorate colitis in mice with decreased levels of TNF-α and IL-6." (PMID 33748287, 2021). "Inflammatory response plays a key role in the activation of IL-6, IL-1β, and TNF-α in colitis." (PMID 35059326, 2021). "Nuclear factor (NF)-κB activation was markedly elevated and resulted in higher expression levels of downstream effectors (C–C motif chemokine ligand 20, interleukin [IL]-1β, IL-6, and tumor necrosis factor [TNF]-α) in colonic epithelial cells isolated from PBLDIEC−/− mice than WT mice with colitis." (PMID 34059646, 2021). "Four peptides, DEDTQAMPFR, MLGATSL, SLSFASR, and MSYSAGF, isolated from egg white exerted anti-inflammatory activities in colitis mouse by inhibiting the production of TNF-α and IL-6 as well as reducing the mRNA-expressions TNF-α, IL-6, IL-17, IL-1β, IFN-γ, and MCP-1." (PMID 34234885, 2021). "In another study, crocin (100 and 200 ppm~1 and 2% w/v) made a significant decrement in the levels of mRNA expression of TNF-α, IL-1β, IL-6, IFN-γ, NF-κB, COX-2, and iNOS and propagated Nrf2 mRNA expression in the colorectal mucosa following dextran sodium sulfate-induced colitis." (PMID 34956439, 2021). "Upon induction of colitis, significant increases in TNF-α, IL-1β, and IL-6 production were observed in mouse colons, and CME treatment could dose-dependently reduce the production of these cytokines." (PMID 34616300, 2021). "Respect to MR-409, MIA-690 showed higher efficacy in inhibiting prostaglandin (PG)E2, 8-iso-PGF2α and serotonin (5-HT) levels, as well as tumor necrosis factor (TNF)-α, interleukin (IL)-6 and nitric oxide synthase gene expression in colon specimens of DSS-induced colitis." (PMID 33510215, 2021). "In cases of steroid-refractory irAEs like colitis, pneumonitis, arthritis, and hepatitis, other immunomodulatory treatments such as blocking antibodies against tumor necrosis factor alpha (TNF-α) or interleukin 6 (IL6) were shown to be effective." (PMID 34208218, 2021). "The mRNA expression levels of TNFα, IL-1β, and IL-6 were increased by nearly 12-, 18-, and 16-fold, respectively, and the secretion levels of TNFα, IL-1β, and IL-6 were elevated by approximately 2-, 10-, and 3-fold, respectively, in DSS-induced colitis." (PMID 34880751, 2021). "Both IL-6 and TNF-α levels in SP-treated mice (P < 0.05) were significantly reduced compared with those in mice in the DSS group, indicating the effective regulation of inflammatory factors by SP in the colonic tissue of mice with colitis." (PMID 34901119, 2021). "Comparing cytokine concentrations, significantly higher level of pro-inflammatory cytokines IL-6 and IL-17A and anti-inflammatory cytokine IL-10 were found in DSS-induced colitis group (p < 0.05, p < 0.001 and p < 0.001, respectively) compared to all other groups." (PMID 33540919, 2021). "While the wild type mice survived DSS-induced colitis, MSC-/- mice showed increased production of pro-inflammatory cytokines (e.g., IL-22, IL-6, TNF-α) in the gut, with more infiltrating immune cells in colon tissues, reduced body weight, and earlier onset of death." (PMID 34992594, 2021). "In this study, consistent with IBD patients, high levels of pro-inflammatory factors (IL-6, IL-1β and TNF-α) were found in mice with DSS-induced colitis, while these pro-inflammatory factors were reduced after treatment with GPH extracts, and high-dose extracts had a stronger inhibitory effect." (PMID 34829046, 2021). "7-hydroxyfrullanolide was also tested in different animal inflammation models, in which oral administration dose-dependently diminished the induced and spontaneous production of TNF-α along with IL-6 in a BALB/c ear edema model and in DSS-induced colitis in mice." (PMID 34208907, 2021).
colitis (continued). "Our recent in vitro and in vivo studies observed that active vitamin D prevented the host from the detrimental effects of overwhelming inflammation by downregulating pro-inflammatory responses (IL-6, TNF-α, IL-8, and IL-1β) in Salmonella-infected IECs and decreased the severity of colitis in mice." (PMID 34943999, 2021). "Moreover, the acute colitis produced a strong induction of mRNA expression levels of TNF-α, IL-1β, IL-6 and CXCL10, ranging from 233.5 ± 24.0% for IL6 to 663.5 ± 195.8% for TNF-α, in WTDSS mice compared to control group (p <0.05)." (PMID 34483912, 2021). "We found that the levels of TNF-α, IL-1β, and IL-6 were significantly increased, however, the production of IL-12 was remarkably decreased in LXN−/− mice during DSS-induced colitis, suggesting TNF-α, IL-1β, IL-6 and IL-12 involved in DSS-induced colitis in LXN−/− mice." (PMID 32555320, 2020). "To further confirm whether these USP38‐regulated cytokines are responsible for the DSS‐induced colitis in USP38‐KO mice, we neutralized IL‐6 and IL‐23 by peritoneal injection of anti‐IL‐6/IL‐23 antibodies (Abs) in WT or USP38‐KO colitis mice." (PMID 33240782, 2020). "Moreover, uvaol significantly reduces mRNA expression and production of pro-inflammatory cytokines (TNF-α, IL-6, IL-1β, and MCP-1) and infiltration of macrophages in colonic tissues of colitis mice." (PMID 32411289, 2020). "Indeed, in vivo NAC treatment successfully ameliorated acetic acid-induced colitis by reversing pro-inflammatory mediators TNF-α, IL-6, and MPO in rats." (PMID 33224136, 2020). "In addition, the alteration of pro- and anti-inflammatory cytokine levels, such as IL-6, IL-1β, TNF-α, and IL-10, in the serum of the DSS-induced colitis mice were determined by ELISA." (PMID 33391246, 2020). "Intraperitoneal injection of these vesicles to mice treated with TNBS decreases the level of the pro-inflammatory cytokines IL-6, IL-1β, IFN-γ and IL-17a and increases the level of the anti-inflammatory cytokine IL-10 in colonic tissue, thus preventing colitis development." (PMID 32365813, 2020). "Furthermore, the expression of pro-inflammatory cytokines, like IL-6, TNF-α and IL-1β, was decreased in a peptidoglycan-polysaccharide-induced colitis rat model." (PMID 32722619, 2020). "Moreover, tripeptide KPV reduced intestinal inflammation by decreasing IL-1β, IL-6, IL-12, and IFN-γ expressions and attenuated colitis via PepT1." (PMID 32963495, 2020). "Through IL-6/STAT3 signaling pathway, modified PD could inhibit the increased inflammatory response and reduce the severity of colitis lesions." (PMID 32517784, 2020). "Intraperitoneal administration of 5-HT significantly increases the expression of interleukin (IL)-1β and IL-6 and the activity of myeloperoxidase (MPO) by activating 5-HT3 and 5-HT4 receptors in colonic mucosa of colitis mice, while blocking the signal can reduce the pain." (PMID 32117308, 2020). "Similarly, our study showed that SSW suppressed DSS-induced expression of cytokines, such as IL-6, IL-1β, TNF-α, and COX-2, and besides, alleviated DSS-induced colitis symptoms in mice." (PMID 32708415, 2020). "As a derivative of coptisine, (±)-8-ADC (75, 150, and 300 mg/kg) treatment activates the transcriptional activity of X-box binding protein 1 and decreases NF-κB expression, subsequently reduces secretion of myeloperoxidase, TNF-α, IL-6 and IL-1β in the colon of DSS-induced colitis mouse." (PMID 32063999, 2020). "Dex treatment strongly upregulated the expression of the cytokines TNFα, IL-1β and IL-6 but not IL-10 in the course of DSS colitis compared with that in the control group." (PMID 32290362, 2020). "Notably, the plasma levels of IL-6, IL-1β, and TNFα from DSS colitis mice were significantly diminished in mice that received anti-Myl9/12 Ab treatment in comparison to those that received control Ab treatment." (PMID 33584659, 2020).